SEMA3A (semaphorin 3A)
Diseases named in the same sentence as SEMA3A in open-access papers (continued):
Sharing a sentence is not in itself a finding about the gene and the disease.
tumor (continued). "For instance, semaphorin 3A and semaphorin 4D have been extensively documented to promote tumor progression, immune suppression, and nerve–tumor interactions, contributing directly to PNI progression." (PMID 41009819, 2025). "Specifically, research has highlighted that the degradation of perlecan-Sema3A-PlexinA1-Nrp1 receptor complexes on prostate cancer cells by MMP7 regulates tumour cell migration by destabilising cell junctions." (PMID 40634736, 2025). "For each tumour tissue, we identified 1 mm2 area exclusively occupied by either classical or basal-like/squamous cells and evaluated SEMA3A in the epithelial and stromal compartments." (PMID 38670629, 2024). "After multiple failed clinical trials, research shifted from an anti-angiogenic approach to tumor vessel normalization though the blocking of the VEGF–VEGFR2 axis with Semaphorin 3A (SEMA3A) which targets nucleolin." (PMID 39199647, 2024). "In this study, we characterize the role of the secreted protein SEMA3A in controlling tumor-specific CD8+ T cells, highlighting important conclusions concerning its function." (PMID 38609390, 2024). "To optimize the timing to retrieve viral genomes, we generated a pilot pool composed of 50 randomly chosen AAV vectors, including the positive control Semaphorin3A (Sema3A), which is known to inhibit cell invasion and tumor growth in vivo." (PMID 38195652, 2024). "Tumors with estrogen receptor expression exhibited significantly lower levels of SEMA3A expression in the tumor cells (p = 0.0024)." (PMID 38263416, 2024). "Overall, we show here that SEMA3A is a functional marker of aggressive PDAC that promotes tumour progression through modification of the local microenvironment and by enhancing the metastatic competence of neoplastic cells." (PMID 38670629, 2024). "The study demonstrated positive SEMA3A expression in tumor vessels across all subtypes in 91 out of 98 cases, suggesting its involvement in endothelial cell function." (PMID 38263416, 2024). "In our preclinical models, tumour cells derived SEMA3A contributed to define an immunosuppressive TME with abundant macrophages and reduced density of CD8+T cells." (PMID 38670629, 2024). "SEMA3A high tumours responded poorly to both gemcitabine and CSF1R inhibition as monotherapy, and only the combination significantly extended the survival of the mice." (PMID 38670629, 2024). "NR2F2‐AS1 overexpression inhibited tumor volume and tumor weight, which was reversed by SEMA3A silencing." (PMID 39177014, 2024). "Others have indeed shown that anti-NRP1 antibodies can affect tumor growth in mouse models, likely by both inhibiting Treg cells and, as we show here, by decreasing the effects of SEMA3A on CD8+ effector T cells." (PMID 38609390, 2024). "An increased expression of Sema3a in cancer cells inhibits angiogenesis and tumor growth by reducing tumor vasculature." (PMID 39285385, 2024). "First, we tested the effect of CSF1R inhibition alone or in combination with gemcitabine on the survival of mice bearing tumours from either Sema3a high or low cells." (PMID 38670629, 2024). "Here the authors investigate how these interactions affect CD8+ T cells in tumour immunity, showing that NRP-1, Plexin-A1 and Plexin-A4 are upregulated on T cells allowing tumour derived SEMA3A to inhibit CD8+ T cell migration and function." (PMID 38609390, 2024). "Consistent with our findings in the mouse models, transcriptional signatures of tumour-associated macrophages (TAMs) were significantly enriched in SEMA3A high tumours." (PMID 38670629, 2024). "CD133 upregulated SEMA3A and SREBF1 by 3- and 5-fold, respectively; these genes have been implicated in the tumor progression of different cancers." (PMID 38727313, 2024). "Immunofluorescence staining showed SEMA3A was mainly located around the core of the tumor, with SEMA3A rich areas containing many CD8+ T cells." (PMID 38609390, 2024).
tumor (continued). "The most significant differences in SEMA3A expression were observed within the tumor cells themselves, indicating its potential role in tumor proliferation and cancer progression." (PMID 38263416, 2024). "Further experiments revealed that the inhibitory effects of NR2F2‐AS1 overexpression on EMT, migration, invasion of OSCC cells, and angiogenesis of HUVECs as well as tumor growth and metastasis in mice were mediated via the miR‐32‐5p/SEMA3A axis." (PMID 39177014, 2024). "SEMA3A expression in tumor vessels was found in 91 out of 98 cases; in 20 cases the expression was strongly positive, in 37—weakly positive and in 34—focal expression was present." (PMID 38263416, 2024). "Collectively, these findings indicate that NR2F2‐AS1 upregulation suppressed tumor growth in nude mice by enhancing SEMA3A expression." (PMID 39177014, 2024). "Conversely, significantly fewer tumor-specific T cells homed to and infiltrated SEMA3A-overexpressing tumors." (PMID 38609390, 2024). "Sema3A, a semaphorin involved in angiogenesis, has been shown to enhance the efficacy of anti‐angiogenic therapy when its expression is restored in tumours." (PMID 39456119, 2024). "In the tumor, SEMA3A was predominantly expressed by smooth muscle cells within the tunica media of tumor vasculature but also in areas of fibromuscular stroma." (PMID 38609390, 2024). "Here we demonstrate that Neuropilin-1 (NRP1) and Plexin-A1 and Plexin-A4 are upregulated on stimulated CD8+ T cells, allowing tumour-derived SEMA3A to inhibit T cell migration and assembly of the immunological synapse." (PMID 38609390, 2024). "SEMA3A expression correlated positively with Ki67 levels in tumor cells (p = 0.0005, R Spearman 0.338)." (PMID 38263416, 2024). "We observed a significant positive correlation between SEMA3A expression and Ki67 levels in both tumor cells and tumor vessels." (PMID 38263416, 2024). "On depletion of CD8+T cells, the combination lost its antitumour activity in Sema3a expressing tumours, thereby suggesting that its efficacy was at least in part mediated by the increased infiltration of T cells." (PMID 38670629, 2024). "We therefore suggest that SEMA3A trap CD8+ T cells following their infiltration to perivascular areas within the tumor." (PMID 38609390, 2024). "Tumors with progesterone receptor expression exhibited significantly lower levels of SEMA3A expression in the tumor cells (p = 0.0097)." (PMID 38263416, 2024). "SEMA4G levels were enriched in classical tumours while the expression of SEMA3A, SEMA3C and SEMA3F was significantly enriched in basal-like PDAC." (PMID 38670629, 2024). "SEMA3A provides mouse PDAC cells with greater metastatic competence and favours intratumoural infiltration of tumour-associated macrophages and reduced density of T cells." (PMID 38670629, 2024). "While it has been established that Plexin-A4 plays a role in inhibiting tumor angiogenesis through Sema3A signaling, it is important to note that there is a need for additional research in the context of vascularization-mediated bone regeneration." (PMID 38078001, 2023). "For example, sema3A, which normally inhibits tumor cell invasiveness when signaling through its plexin-A1 receptor, induces tumor cell invasiveness following the association of its plexin-A1 receptor with cell surface-associated perlecan." (PMID 37627074, 2023). "SEMA3A is a candidate tumour suppressor gene that regulates the antitumour response of the immune system." (PMID 37685898, 2023). "On the other hand, SEMA3A secreted by a variety of human tumor cells (lung, breast, prostate, glioblastoma, and colorectal cancer cells) has been shown to inhibit tumor-CD4+/CD8+ lymphocyte interactions and T-cell activation and proliferation." (PMID 38067240, 2023). "Several class-3 semaphorins such as sema3A, sema3B and sema3F have been found to function as potent inhibitors of tumor angiogenesis and consequently as inhibitors of tumor progression." (PMID 36658114, 2023).
tumor (continued). "The Sema3A/NRP1 axis contributes to promote angiogenesis, recruitment of tumor-associated macrophages, and tumor-induced immune privilege." (PMID 37788099, 2023). "Sema3A is classically described as a collapsing factor and a mediator of axon repulsion, but its roles have been extended to tumor growth, invasion, and angiogenesis." (PMID 37788099, 2023). "Blockade of Sema3A/Nrp1 signaling prevents macrophages from entering hypoxic tumor regions, inhibits angiogenesis and restores anti-tumor immunity." (PMID 37143720, 2023). "Our group has previously identified the tumor-suppressive role of Sema3A in head and neck cancer cells." (PMID 35347234, 2022). "Sema3A has the ability to regulate tumor blood vessels, alleviate tumor hypoxia, and inhibit tumor growth." (PMID 36071472, 2022). "NRP1 acts as a cell-surface receptor for Sema3A and affects cell survival and migration, which are essential for tumor progression and EMT." (PMID 35775491, 2022). "Several semaphorins including Sema3a, Sema3f, Sema3g and Sema6a have been reported to exert tumor growth-inhibiting activities while several others such as Sema4d and Sema6d have been associated with tumor-promoting functions in various cancer types." (PMID 35223842, 2022). "An interesting mechanism in PCa-macrophages crosstalk involved semaphorin 3A (SEMA3A) which is produced by cancer cells and recruit monocytes to the tumor site where acquire a pro-tumoral CD68+ M2-like phenotype." (PMID 36338516, 2022). "Sema3A and Sema3B, constitutively distributed on immune cells, binding to Nrp-1, contribute to immune escape from anti-tumor effects of CD8+ CTL." (PMID 35155237, 2022). "For example, by antagonizing the interaction between NRP1 and Sema3A, Pan and colleagues, demonstrated an inhibition of tumor angiogenesis and tumor growth in vivo, effects that were compounded when combined with antibodies directed against VEGF binding." (PMID 36970722, 2022). "The expression of LINC00460/EME1/HNRNPAB/PLAUR and SEMA3A was higher in most tumour tissues, including LUAD, than in the corresponding control tissues (P < 0.001)." (PMID 36091160, 2022). "For instance, the restriction of TAMs to normoxic regions by blocking the Sema3A/Neuropilin-1 pathway reduced tumor pro-angiogenic and immunosuppressive functions and inhibited tumor development and metastasis." (PMID 35574385, 2022). "Expression of SEMA3A gradually decreases during the transition of premalignant lesions to the tumor, consistent with the development of a dysfunctional abnormal tumor vasculature system during this course." (PMID 36143975, 2022). "In cancer cells, full-length Sema3A plasmids transfection suppressed tumorigenesis and blocked metastasis of tumor cells that were implanted into mice." (PMID 35347234, 2022). "Sema3A derived from GBM elicits TAMs (microglial cell) accumulation, and antibody blockage of Sema3A (anti-Sema3A, F11) exhibits notable tumor inhibitory effect through downregulating TAMs recruitment in patient-derived xenograft (PDX) models." (PMID 35155237, 2022). "Further investigations are needed to examine the role of lung-derived Sema3A in osteoclast differentiation during tumor growth." (PMID 36142564, 2022). "It has also been found that the SALL3 gene, is upregulated by stilbenes, which down-regulates DNMT3A (DNA (cytosine-5)-methyltransferase 3A), binding to the promoters of tumour suppressor genes such as SEMA3A." (PMID 36557789, 2022). "On the other hand, Sema3A, as a tumor suppressor, has been reported to restrict the proliferation of pro-tumoral macrophages and repress tumor growth." (PMID 35155237, 2022). "In breast cancer, Sema3A is a tumor suppressor, downregulated in tumor and negatively correlated with tumor stage." (PMID 35155237, 2022). "Although semaphorin-NRP1 signaling is not essential for vascular development in mouse embryos, semaphorin 3A (SEMA3A) participates in modulating tumor angiogenesis in mouse cancer models." (PMID 35600336, 2022).
tumor (continued). "NRP1 recruits and subsequently arrests pro-tumorigenic TAMs in response to Sema3A-producing hypoxic tumor regions through plexinA1/plexinA4 signaling and VEGFR1 activation." (PMID 35651620, 2022). "For example, Maione and colleagues have shown that reduction of hypoxia by overexpression of semaphorin 3A (Sema3A) contributed to normalised tumour blood vessels, which pave the way for T cell trafficking into tumours." (PMID 33917287, 2021). "In tumour angiogenesis this balance falls in favour of VEGF, but in studies that followed the targeted delivery of Sema3A, tumour angiogenesis was inhibited and vessels regained a functional morphology." (PMID 33828258, 2021). "In hypoxic areas of tumor hypoxia-induced SEMA3A attracts TAMs by activating VEGFR1 through the composition of neuropilin-1 (Nrp1) and plexinA1/plexinA4." (PMID 34209679, 2021). "We also demonstrated a significant correlation between Sema3A levels and tumor size and the number of lesions." (PMID 33546237, 2021). "In some cases (e.g. Sema3A), the systemic delivery of these “inhibitory” semaphorins for cancer therapy has been validated in preclinical studies resulting in inhibition of tumor progression." (PMID 33537086, 2021). "Depending on the tissue type, semaphorin 3A stimulation can enhance or inhibit angiogenesis and migratory pathways in tumor cell populations." (PMID 34270956, 2021). "For example, it was shown that Sema3A impedes tumor cell migration in breast cancer, and is also overexpressed in metastatic cells of patients with prostate cancer and lung cancer." (PMID 33546237, 2021). "In low-grade tumor samples, cells in the basal layer of the mucosa were also lightly stained with Sema3A, but Seama3A expression intensified upon moving apically, reaching its highest level on apical cells exfoliating to the urine." (PMID 33546237, 2021). "Tumor cells present Sema3A and inhibits immune anti neoplastic response by blocking T cells adhesion capabilities, proliferation, and cytokine production." (PMID 33546237, 2021). "Consistently, histopathological analyses proved that the expression of Sema3A in bladder tissue increases with the tumor grade." (PMID 33537086, 2021). "NRP1 also acts as a receptor for the class 3 semaphorin (SEMA3A) to regulate vascular permeability and vessel maturation during tumor angiogenesis." (PMID 33850110, 2021). "Specifically, attempts have been made to decipher the role played by Sema3A in tumor growth and propagation." (PMID 33546237, 2021). "In a mouse model of breast cancer, SEMA3A overexpression in 4T1 cancer cells decreased tumor volume to 61% and promoted the accumulation of M1-like (CD11b+Ly6G−lowMHCIIhigh) macrophages in the tumor compared to 4T1-control tumors." (PMID 34209679, 2021). "Sema3A has been shown to promote tumor growth by attracting NRP-1+ TAMs to the hypoxic tumor core, suppressing the activity of NRP-1+ CD8+ T cells and stimulating Treg activity." (PMID 33266104, 2020). "In cancer context, SEMA3A is reported to play pleiotropic activities controlling tumour cells, tumour vessels and infiltrating inflammatory cells." (PMID 32241267, 2020). "In the case of tumor-associated macrophages (TAMs), NRP-1, together with PlexinA1/A4, acts as a guide for these cells to migrate to the hypoxic core of the tumor in response to semaphorin 3A (Sema3A), where they exert tumor-promoting functions." (PMID 33266104, 2020). "In contrast, other researchers have shown that Sema3A alters tumor cell behavior directly by influencing migration and growth, or indirectly by interfering with tumor angiogenesis and the immune response." (PMID 32192122, 2020). "Functional blocking studies targeting Sema3A have also been utilized, highlighting the role of the pathway in tumor progression." (PMID 33302912, 2020).
tumor (continued). "The data presented here suggest that SEMA3A has a tumor suppressor function in OPC because our Kaplan–Meier survival analysis showed that low SEMA3A expression significantly correlated with shorter survival time in OPC patients." (PMID 32842711, 2020). "For instance, SEMA3A induces invasion and correlates with poor survival in both pancreatic and colon cancers, but inhibits tumour invasion and metastasis in patients with prostate, breast, and lung cancer." (PMID 32241267, 2020). "A recent study showed Sema3A expression in a variety of cancer cell lines and demonstrated that secretion of Sema3A by tumor cells enables manipulation of their microenvironment through suppression of T-cell activation." (PMID 32192122, 2020). "Recently, Semaphorin 3A (SEMA3A) has been shown to regulates cell adhesion, cell motility, angiogenesis, immune responses, and tumor progression." (PMID 32842711, 2020). "Patient age, tumor grade, status of IDH mutation and expression of seven genes (SEMA3A, SEMA3D, SEMA3F, SEMA3G, ITGB3, ITGA5, and VEGFA) significantly correlated with patient OS (p < 0.05)." (PMID 33036421, 2020). "Down-regulation of SEMA3A expression in cancerous cells enhances angiogenesis and tumor progression, representing that it acts as an endogenous suppressor of the angiogenesis." (PMID 31205625, 2019). "A wide range of studies on SEMA3A also have been performed in different physiological and pathological processes, including cardiogenesis, angiogenesis, vasculogenesis, tumor metastasis, osteoclastogenesis and immune regulation." (PMID 30971898, 2019). "It was found that SEMA3A can attract tumor-infiltrating macrophages into the hypoxic tumor core, where they are induced to differentiate towards the M2 immune-suppressive and cancer promoting phenotype." (PMID 30658382, 2019). "In cancer context, SEMA3A plays pleiotropic activities controlling tumor cells, tumor vessels and infiltrating inflammatory cells." (PMID 30658382, 2019). "The role of NRP1 expressed by TAMs in controlling their entry into tumor hypoxic regions in response to Sema3A has been investigated." (PMID 31052281, 2019). "Together with plexins (plexin-A1) and neuropilins (Nrp-1 and Nrp-2), semaphorins (including SEMA3A) have the ability to interrupt vascular formation and tumor vascularization." (PMID 30971898, 2019). "In ECs of premalignant lesions, SEMA3A is an endogenous angiogenesis inhibitor whose expression is lost during tumor progression." (PMID 30717262, 2019). "It has been reported that SEMA3A acts as an anti-tumor agent since it suppresses angiogenesis by competing with VEGF for identical receptors on endothelial cells." (PMID 31205625, 2019). "It induces the apoptosis of monocyte-derived macrophages, while tumor-cell-secreted Sema3A has been found to inhibit primary human T-cell proliferation and cytokine secretion." (PMID 31052281, 2019). "Expression of SEMA3A normalizes pericyte coverage and at the same time reduces angiogenesis and tumor growth." (PMID 30717262, 2019). "For example, upon SEMA3A overexpression in tumor cells, it selectively expanded the population of M1-like pro-inflammatory macrophages derived from NRP1+ monocytes, which further led to the recruitment of NK and CD8+ cytotoxic T cells." (PMID 30658382, 2019). "In several experimental animal models, it has been indicated that the systemic and intra-tumoral delivery of SEMA3A prevents tumor angiogenesis and tumor development." (PMID 31205625, 2019). "Interaction of Nrp-1 with its ligand semaphorin-3A inhibits migration and tumour-specific lytic function of cytotoxic T lymphocytes." (PMID 31350404, 2019). "Several data support a vessel-regulating and tumor suppressor function of SEMA3A, but there are discordant findings." (PMID 30658382, 2019). "In particular, while it has been shown by different groups that SEMA3A can attract NRP1-expressing tumor-infiltrating monocytes, data diverge on the functional role of these cells." (PMID 30658382, 2019).